GATA6 (GATA binding protein 6)
Diseases named in the same sentence as GATA6 in open-access papers (continued):
Sharing a sentence is not in itself a finding about the gene and the disease.
diabetes (26 papers, 2015 to 2026). "In the past, it was known that monogenic diabetes with GATA6 mutation often manifested as neonatal diabetes and abnormal pancreatic development." (PMID 37204622, 2024). "Monogenic diabetes caused by GATA6 mutations were almost described as neonatal diabetes, and the phenotypic spectrum has expanded since then." (PMID 37204622, 2024). "With the development of gene diagnosis technology, in recent years, a few reports have found that monogenic diabetes with GATA6 mutations can be manifested in children and even adults, but there is no report of adult diabetes as the proband." (PMID 37204622, 2024). "Carries with GATA6 mutations (n = 55) have a variable spectrum of diabetes, ranging from neonatal (72.7%), childhood-onset (20%) to adults-onset (7.5%)." (PMID 37204622, 2024). "We hope that this study will enable treating physicians to increase the understanding of monogenic diabetes with GATA6 mutations." (PMID 37204622, 2024). "Inclusion criteria were: GATA6 mutations patients with diabetes and/or pancreatic developmental defect where the full text was available." (PMID 37204622, 2024). "In conclusion, there are various types of diabetes with GATA6 mutations, which can also occur in adult diabetes." (PMID 37204622, 2024). "By conducting these studies, researchers can elucidate the mechanisms by which GATA6 mutations disrupt pancreatic function and potentially identify therapeutic targets for developing novel interventions for monogenic diabetes associated with GATA6 variants." (PMID 39596087, 2024). "LOF in GATA4 and GATA6 are associated with pancreatic agenesis/hypoplasia and diabetes, along with congenital heart abnormalities and several cancers." (PMID 35052457, 2022). "Heterozygous GATA6 mutations in humans have been identified as a major cause of pancreas agenesis that often results in diabetes." (PMID 36339450, 2022). "GATA6 mutations have been previously linked to diabetes and pancreatic agenesis and it was shown to have a role in endoderm formation, pancreas development, and β-like cell functionality." (PMID 33479343, 2021). "Mutations in GATA6 should be strongly considered in cases of diabetes due to pancreatic hypoplasia or agenesis, and potentially affected family members should be tested regardless of phenotype." (PMID 28049534, 2017). "Although uncommon, it is important to consider GATA6 mutations and investigate for pancreatic agenesis/hypoplasia if neonatal diabetes is seen in combination with congenital heart defects or other anomalies." (PMID 27098067, 2016). "Less frequently, mutations of the GATA6 gene, located on chromosome 18 cause a form of permanent neonatal diabetes resulting from pancreatic hypoplasia or agenesis." (PMID 27098067, 2016). "We report an infant presenting with neonatal diabetes resulting from a de novo heterozygous mutation in the GATA6 gene." (PMID 27098067, 2016). "We report a case of neonatal diabetes resulting from a de novo mutation of the GATA6 gene resulting in pancreatic hypoplasia." (PMID 27098067, 2016). "As a rare type of monogenic diabetes, GATA6 mutations is mostly reported as cases." (PMID 37204622, 2024). "Therefore, the formation, differentiation, maturation, and dysfunction of the endoderm and pancreas caused by GATA6 mutations is an important pathological basis for GATA6 mutation monogenic gene diabetes." (PMID 37204622, 2024). "Furthermore, we reviewed related literature to summarize the clinical and genetic characteristics of monogenic diabetes with GATA6 mutations (n = 39) in order to improve clinicians’ understanding of the disease." (PMID 37204622, 2024). "His diabetes resulted from a de novo mutation of the GATA6 gene resulting in pancreatic hypoplasia." (PMID 27098067, 2016).
diabetes (continued). "Thus, GATA6 haploinsufficiency needs to be strongly considered as a potential cause in cases of diabetes secondary to abnormal pancreas development and, if confirmed, a thorough, multi-system assessment, particularly cardiac, should be performed to evaluate for other abnormalities." (PMID 28049534, 2017). "Because these factors—including GLIS3, PAX6, GATA6, HNF1B, and NEUROG3—are pleiotropic regulators active in multiple organ systems, their deficiency rarely causes isolated diabetes." (PMID 41614934, 2026). "Syndromic Diabetes: Arises from mutations in pleiotropic transcription factors (GLIS3, GATA6, HNF1B) or metabolic transporters (SLC19A2, WFS1)." (PMID 41614934, 2026). "Our genotype and phenotypic analysis of GATA6 mutant monogenic diabetes shows that there is significant heterogeneity in both clinical phenotype and genotype–phenotype correlation." (PMID 37204622, 2024). "At the same time, even family members with the same GATA6 allele mutation have different clinical manifestations, showing significant phenotype-clinical differences, which brings great challenges to the diagnosis of GATA6 mutant monogenic diabetes." (PMID 37204622, 2024). "The main components of GATA6 syndrome are diabetes mellitus, exocrine pancreatic insufficiency, and developmental abnormalities of the digestive and cardiovascular systems." (PMID 39596087, 2024). "Previous studies have found that GATA4 and GATA6 transcription factors in the pancreas play a key role in neonatal diabetes." (PMID 36650523, 2023). "With further investigation/follow-up after the genetic diagnosis was made all patients had features consistent with their syndrome except the patient with GATA6 diabetes." (PMID 34789499, 2022). "As for the genetic susceptibility for diabetes, ABCC8/KCNJ11 is associated with neonatal diabetes, GATA6 is associated with pancreas agenesis, and HNF1A is associated with monogenic diabetes." (PMID 28744848, 2017). "Similarly, GATA6 and HNF1B mutations present with diabetes associated with structural defects in the heart and kidneys, respectively." (PMID 41614934, 2026). "In this case, the new GATA6 mutant paternal family shows adult diabetes and pancreatic dysplasia." (PMID 37204622, 2024). "Likewise, heterozygous mutations in other transcription factors (e.g., GATA6, HNF1B) have been reported to cause diabetes as a consequence of their effects on early pancreatic development." (PMID 38509065, 2024). "GATA6 syndrome is characterized by a combination of neonatal diabetes mellitus (up to 72.7% of cases), exocrine pancreatic insufficiency (up to 67.3% of cases), and congenital developmental anomalies including the heart (up to 89.9% of cases) and the gastrointestinal tract." (PMID 39596087, 2024). "In our case, the cause of NDM was not identified initially with sequencing most common diabetes genes, while whole-exome sequencing revealed a pathogenic, heterozygous variant in the GATA6 gene." (PMID 39596087, 2024). "During the genetic counseling of the patient’s family, the parents reported no family history of diabetes, and genetic testing revealed no changes in the GATA6 gene in the parents, whereby a described pathogenic variant in the child arose de novo." (PMID 39596087, 2024). "However, GATA6 heterozygous phenotypes range from total pancreatic agenesis to isolated diabetes in young adulthood." (PMID 30629940, 2019). "Likewise, Hnf1b, Gata4/Gata6, Pdx1 or Mnx1-deficient mice fail to develop pancreas of normal size and rather develop diabetes." (PMID 39322760, 2024). "Another study investigating differential monocyte gene expression in individuals with diabetes identified IRF1, GATA6, SP11, EPAS1, NFKB2, and STATB3 as key affected transcription factors." (PMID 40476695, 2025). "Key examples include IRF1, GATA6, SPI1, EPAS1, NFKB2, and STAT5B, which are involved in immune response, cell differentiation, and metabolic regulation, all of which are critical in diabetes pathogenesis." (PMID 39877357, 2024).
diabetes (continued). "De novo variants in this gene occur in 73.6% of all syndrome cases, and in most cases of GATA6 syndrome, the proband does not have a family history of diabetes mellitus." (PMID 39596087, 2024).
pancreatic agenesis (24 papers, 2013 to 2025). Partial agenesis of the pancreas is characterized by the congenital absence of a critical mass of pancreatic tissue. "GATA6 is required for the development of multiple mesoderm and endoderm derived organs and some CHD patients with heterozygous GATA6 mutations have comorbidities including pancreatic agenesis, neonatal diabetes, or congenital diaphragmatic hernia." (PMID 39026742, 2025). "Numerous inactivating mutant alleles of GATA6 have been associated with the occurrence of pancreatic agenesis in humans." (PMID 39717718, 2025). "For example, GATA6 (associated with pancreatic agenesis and congenital heart defects, MIM #600001) has 10 pLoFs in UKB, of which eight are located before the first inframe ATG downstream of the canonical start codon, at Met147." (PMID 38671509, 2024). "The most common cause of NDM due to pancreatic agenesis is heterozygous mutation in the GATA6 transcription factor gene." (PMID 34584998, 2021). "used hiPSCs derived from a patient with pancreatic agenesis associated with a heterozygous GATA6 frameshift mutation, which leads to production of a truncated protein." (PMID 34295307, 2021). "Contrary to what has been observed in the mouse 60, mutations of the human GATA6 gene have been associated with pancreatic agenesis 61, 62, 63, consistent with GATA6 as a MPC marker in human." (PMID 31631582, 2019). "Heterozygous de novo mutations in GATA6 are the most frequent cause of pancreatic agenesis in humans." (PMID 30629940, 2019). "Haploinsufficiency of the GATA6 transcription factor gene was recently found to be the most common cause of pancreatic agenesis, a rare cause of neonatal diabetes mellitus." (PMID 28049534, 2017). "GATA6, the most commonly-mutated gene in pancreatic agenesis in humans, also showed significant differential expression in DE (log2 FC = 12.1 p = 8.6 × 10−6)." (PMID 27246810, 2016). "In both probands, the novel GATA6 variants are de novo and heterozygous, similar to pervious GATA6 variants found in pancreatic agenesis, supporting a mechanism of haploinsufficiency in humans that is distinct from rodent models." (PMID 25706805, 2015). "Overall, these studies have established that GATA6 haploinsuffiency is a major cause of syndromic pancreatic agenesis and point to a crucial role for GATA6 in pancreatic development." (PMID 24986330, 2014). "De novo mutations were identified by exome sequencing of affected proband/unaffected, unrelated parent trios before Sanger sequencing in a wider cohort showed that heterozygous GATA6 mutations are the most common cause of pancreatic agenesis." (PMID 24051999, 2013). "Finally, an insufficiency in the GATA-binding protein 6 (GATA6) was the latest genetic defect linked to pancreatic agenesis." (PMID 39421339, 2024). "Similarly, GATA6 mutations cause pancreatic agenesis leading to PNDM, together with abnormalities of the heart, biliary tract, and gut development." (PMID 34079523, 2021). "Mutations in GATA6 are the most frequent cause of pancreatic agenesis." (PMID 32245430, 2020). "Similarly, iPSCs from a pancreatic agenesis patient harboring a GATA6 mutation were differentiated to investigate the pancreatic developmental defect revealing that GATA6 plays an important role during endoderm formation and function of β-cells." (PMID 30930950, 2019). "Heterozygous inactivating mutations in GATA6 were identified through a whole exome sequencing strategy in 15/27 (56%) individuals with pancreatic agenesis, defined as NDM requiring insulin treatment and exocrine pancreatic insufficiency requiring enzyme replacement." (PMID 28049534, 2017). "Exome sequencing has revealed GATA6 haploinsufficiency as the most common cause of pancreatic agenesis, and the expectation is that genome-wide analysis by next generation sequencing will rapidly uncover additional new causal genes to assist in the diagnosis and clinical management of NDM." (PMID 24051999, 2013).
pancreatic agenesis (continued). "In addition, severely damaging nonsense or truncating frameshift variants in GATA6 may result in biliary system abnormalities, congenital diaphragmatic hernia, pancreatic agenesis, and/or monogenetic diabetes." (PMID 40076735, 2025). "Three of these (GATA4, GATA6 and HNF4A) are known causes of pancreatic agenesis and/or diabetes in humans when mutated and are involved in endoderm, liver and pancreas specification." (PMID 37973953, 2023). "Since GATA6 haploinsufficiency resulting in pancreatic agenesis in patients cannot be recapitulated in mice, effects of GATA6 gene dosage on pancreatic differentiation in vitro helped in understanding the clinical presentation of different patients." (PMID 34079523, 2021). "GATA6 also is critical for endodermal development, and some CHD patients with damaging GATA6 variants also have pancreatic agenesis, congenital diaphragmatic hernia or other abdominal malformations." (PMID 33054971, 2020). "However, the concurrent elimination of both GATA4 and GATA6 in the pancreas led to severe pancreatic agenesis." (PMID 39717718, 2025). "These researchers generated a hiPSC line derived from a pancreatic agenesis patient, harboring a heterozygous 4 bp duplication in exon 2 of GATA6 leading to a premature STOP codon, a genetically matched control line, and an identically artificially-mutated ESC line." (PMID 34295307, 2021). "In contrast, while haploinsufficiency of GATA6 is a common cause of pancreatic agenesis in humans, in mice Gata6 knockout does not result in abnormal pancreatic development." (PMID 31006513, 2019). "We additionally derived hiPSCs from two GATA6 heterozygous pancreatic agenesis patients." (PMID 30629940, 2019). "To date, pathogenic variants in six genes (PTF1A [MIM: 615935], PDX1 [MIM: 260370], GATA6 [MIM: 600001], GATA4 [MIM: 600576], HNF1B [MIM: 137920], and RFX6 [MIM: 615710]) have been reported to severely affect pancreatic development and result in pancreatic agenesis." (PMID 31006513, 2019).
congenital heart disease (21 papers, 2013 to 2025). A heart disease that is present at birth. "GATA6 variants are associated with pancreatic hypoplasia/aplasia, congenital heart disease, and biliary tract disorders." (PMID 40476119, 2025). "Haploinsufficiency for GATA6 is associated with congenital heart disease (CHD) with variable comorbidity of pancreatic or diaphragm defects, although the etiology of disease is not well understood." (PMID 39026742, 2025). "Although GATA6 variants have been mainly implicated in conotruncal heart defects, GATA6 loss-of-function variants were identified in a family with BAV." (PMID 37187784, 2023). "Mutations in GATA6 are related to congenital heart defects, including persistent truncus arteriosus and atrial septal defects." (PMID 37662558, 2023). "Over 30 mutations in GATA6 gene are associated with congenital heart disease, indicating the pivotal regulating function of GATA6 in heart." (PMID 35185581, 2022). "Our previous researches have found that five mutation sites in GATA4 gene promoter, two mutation sites in GATA5 gene promoter, and two mutation sites in GATA6 gene promoter were associated with congenital heart disease." (PMID 33684162, 2021). "The association with the genes NKX2-5, NOTCH1, GATA4, GATA6 and HAND1 links trabeculation to congenital heart disease (CHD)." (PMID 39567769, 2024). "Genome-wide association studies and experimental mouse models implicate the MIB1 and GATA6 genes in congenital heart disease (CHD)." (PMID 39057643, 2024). "Therefore, the expression and the role of GATA5 partially overlap that of GATA4 and GATA6 during development, making it an important molecular factor for different congenital heart diseases." (PMID 40076735, 2025). "The conserved zinc finger transcription factor proteins, which include GATA binding protein 5 (GATA5) and GATA binding protein (GATA6) play important roles in embryonic development and their inactivation may result in congenital heart defects (CHDs)." (PMID 40076735, 2025). "GATA6 duplications and /or mutations have been seen in cases with congenital heart disease but also non-affected individuals, suggesting incomplete penetrance and variable expressivity." (PMID 36050713, 2022). "We report an infant presenting with neonatal diabetes associated with congenital heart disease, absent gall bladder and an inguinal hernia resulting from a de novo heterozygous mutation in the GATA6 gene." (PMID 27098067, 2016). "Moreover, miR- 499 and miR-1275 may play a significant role in cardiac muscle mitochondrial functioning whereas miR-23b via targeting the GATA6/IGF-1 axis may promote congenital heart disease development." (PMID 38256030, 2024). "Further research is required to understand the mechanisms by which GATA6 regulates CXCR7 and CXCL12–CXCR4 signaling during endocardial cushion formation and in congenital heart disease." (PMID 39253784, 2024). "Other genes encoding GATA family cardiac factors, such as GATA4 (GATA-binding protein, 4; 8p23.1; OMIM*6005769) and GATA6 (GATA-binding protein, 6; 18q11.2; OMIM*601656) were observed in human congenital heart defects." (PMID 28883797, 2017). "In this study, we show that Gata6 haploinsufficiency results in highly penetrant BAV and characterize the phenotype to OFT alignment anomalies, including a membranous VSD, a common component of congenital heart disease in humans." (PMID 39253784, 2024).